ALB (albumin)
Diseases named in the same sentence as ALB in open-access papers (continued):
Sharing a sentence is not in itself a finding about the gene and the disease.
tumor (continued). "The assessment of local controllability and survival showed the anti-tumor efficacy of the procedure, and the analyses of the serum biochemical factors and hepatic function, including the Child–Pugh score and albumin–bilirubin (ALBI)-grade, demonstrated its safety." (PMID 33066141, 2020). "The multivariate Cox regression model revealed that PM2.5 ≥ 36 μg/m3 (p = 0.004), Child–Pugh score (p < 0.001), albumin (p < 0.001), macrovascular invasion (p < 0.001), tumor number (p < 0.001), and tumor size (p < 0.001) were critical risk factors for mortality." (PMID 31336910, 2019). "Various integrated scores, such as the Okuda, Cancer of the Liver Italian Program (CLIP), TOKYO, JIS, and albumin-bilirubin tumor node metastasis (ALBI-T), incorporate both of these factors, as well as background liver factors representing synthetic and metabolic functions." (PMID 30744175, 2019). "The multivariate Cox regression analysis revealed that PM2.5 ≥ 36 μg/m3 (p = 0.004), Child–Pugh score (p < 0.001), albumin (p < 0.001), macrovascular invasion (p < 0.001), tumor number (p < 0.001), and tumor size (p < 0.001) were significant risk factors for mortality." (PMID 31336910, 2019). "Although lignan accumulation into solid tumors is unknown, tumors commonly possess poorly formed, highly permeable vasculature that results in the accumulation of various macromolecules (e.g., plasma protein albumin) within the tumor microenvironment." (PMID 31060335, 2019). "Moreover, this SWCNTs-based system was conjugated with an albumin-photosensitizer chlorin e6 (Ce6) complex, enabling dual-modality imaging of tumors and improving tumor treatment." (PMID 31182936, 2019). "Those were serum albumin, fibrinogen, C-reactive protein (CRP), the number of white blood cells, neutrophils, lymphocytes, tumor size, and tumor mutational burden." (PMID 31683809, 2019). "The serum albumin level was decreased after tumor inoculation in C57BL/6J mice, but after DBT treatment, it was elevated in a dose-dependent pattern (C group: 2.20 g/dl, T group: 1.38 g/dl, L group: 1.53 g/dl, M group: 1.75 g/dl, and H group: 1.88 g/dl, p < 0.001)." (PMID 31781219, 2019). "In-depth studies of the tumor–inflammation link have identified several blood markers as potential indicators of systemic inflammation and predictors of prognosis in patients with cancer, including the dNLR, C-reactive protein, albumin and LDH." (PMID 31024844, 2019). "We defined grades 1, 2, and 3 as a Fibrosis-4 (FIB4) index of <3.25, 3.26–6.70, and >6.70 as FIB4, respectively, and calculated the FIB4-T in the same manner in which the JIS (Japan Integrated Staging Score) scores and albumin-bilirubin tumor node metastasis (ALBI-T) were calculated." (PMID 30744175, 2019). "In addition, extracellular matrix glycoprotein (Secreted Protein, Acidic and Rich in Cysteine–SPARC), which has a high affinity for albumin and enriched in tumors, can further enhance its tumor deposition." (PMID 30621360, 2019). "Notably, as albumin / CRP ratio was significant associated with other parameters, we therefore performed subgroup analysis according to tumor size, TNM stage, treatment exposure, serum AFP level, and platelet / CRP (platelet to CRP ratio)." (PMID 31164099, 2019). "Interestingly, we find that all of these water-soluble phthalocyanines can specifically bind to albumin, which in turn enhances their tumor-targeting ability." (PMID 31588226, 2019). "Furthermore, albumin encapsulation increased the cellular uptake of nanoparticles in cancerous cells due to specific targeting of albumin on tumor cells." (PMID 31652668, 2019). "According to the results, the preoperative AAPR was significantly associated with tumor diameter (P < 0.001), PLT (P = 0.024), WBC count (P = 0.001), LDH level (P < 0.001), D‐dimer level (P = 0.001), fibrinogen level (P < 0.001), ALB concentration (P < 0.001), and ALP level (P < 0.001)." (PMID 31161711, 2019).
tumor (continued). "It is possible that the sensitivity of the CSP score could be improved by adding factors related to the nutritional status (albumin or prealbumin) and tumor markers (CA125 or AFP)." (PMID 30849974, 2019). "The primary tumor size, serum AFP, and serum albumin were significantly associated with mortality." (PMID 31232945, 2019). "Individual estimates of Log(tumor growth rate [KG]) and baseline factors (e.g., Eastern Cooperative Oncology Group performance status > 0; tumor size; albumin, lactate dehydrogenase, and alkaline phosphatase levels; PD-L1 status; and tumor type) were independent predictors of OS." (PMID 31542806, 2019). "This may be explained by the increased production of cytokines from larger advanced tumors and the increased leakage of albumin from the highly-developed tumor vasculatures." (PMID 31217896, 2019). "With this in mind, we highlight how clinical and experimental albumin-based delivery nanoplatforms may be designed for tackling tumor progression or improving the currently established diagnostic procedures." (PMID 31195727, 2019). "Meanwhile, the reaction of MnO2 with H+ and H2O2 in TME led to the gradual decomposition of these albumin-MnO2 NPs into separate therapeutic albumin complexes with sizes less than 10 nm in order to achieve significantly improved intra-tumour interstitial diffusion for optimized treatment of tumours." (PMID 31671658, 2019). "Moreover, albumin-Ce6-SWCNTs have demonstrated tumor ablation efficacy after irradiation, using a combined PTT-PDT approach." (PMID 31182936, 2019). "The use of a weaker albumin binder might be an ideal compromise leading to increased tumor uptake due to the albumin binding, although with enhanced risk for renal toxicity." (PMID 31671763, 2019). "While the level of LDH may be related to the degree of tumor differentiation (P=0.036), and the level of ALB may be related to the degree of differentiation (P=0.004) and the primary location of the tumor (P=0.019)." (PMID 30627541, 2018). "This demonstrated that SPARC plays a key role in the tumor-targeted delivery of the albumin NPs." (PMID 29732051, 2018). "Thus, formulation of hydrophobic drugs, such as TC in albumin, will not only enhance solubilization in an aqueous medium, but also mediate delivery to tumours." (PMID 29348537, 2018). "nab-paclitaxel is an albumin-bound paclitaxel, with the addition of albumin possibly leading to improved pharmacokinetics, greater specificity of distribution within the tumour, higher intra-tumoural concentration and better efficacy." (PMID 29865155, 2018). "Thus, albumin-based delivery systems exploit the unique binding and transport properties of albumin with the obvious goal of improving penetration into the tumor tissues and accumulation of the hydrophobic drugs at the site of action." (PMID 30602679, 2018). "A very recent work reports that patients with lower serum albumin levels have significantly larger maximum tumor diameters, greater prevalence of portal vein thrombosis, increased tumor multifocality, and higher α-fetoprotein levels with respect to patients with higher albumin levels." (PMID 30524660, 2018). "Moreover, with the conjugated cell-penetrating peptide, the albumin-functionalized particle can further enhance tumor penetration and intratumoral infiltration." (PMID 30340364, 2018). "Based on the fact that electrostatic interactions between chitosan and albumin hydrolyze only in acidic pH (i.e. tumor microenvironment) and that indicates these switchable charge coated NPs reveal a protecting shell toward normal cells and become sticky to tumor cells." (PMID 29545617, 2018). "However, active brain tumors are hungry for nutrients and energy, and the albumin transporter, which uptakes albumin-related compounds into tumor tissues, is highly expressed and can be used for drug delivery and tumor penetration." (PMID 30340364, 2018). "Low values of albumin level and LMR have been associated with advanced stages of the tumour." (PMID 30539028, 2018).
tumor (continued). "The basic principle of its tumor selectivity is considered not to be metabolism, but rather its affinity to albumin and its possible association with transporters such as ABCG2, resulting in its accumulation in lysosomes." (PMID 29441040, 2018). "PET/CT lymphoscintigraphy using 89Zr-nanocolloidal albumin has the potential to improve the preoperative identification of sentinel lymph nodes (SLNs), especially if located in the near proximity of the primary tumour." (PMID 29445878, 2018). "A significantly suppressed xenograft tumor growth without serious side effects, such as weight loss or altered serum biochemistries (albumin, AST, ALT, Cre, and AMY), was observed in the GEM+DFX group." (PMID 29983871, 2018). "Herein, a tumor-targeted multifunctional theranostic agent was synthetized using a facile method, combining four clinically approved materials: artesunate (Arte), human serum albumin (HSA), folic acid (FA), and indocyanine green (ICG)." (PMID 30311065, 2018). "The results indicated T stage, Fuhrman grade, histology, tumor necrosis, targeted therapy as well as hemoglobin, serum albumin, NLR, PLR and LMR as continuous variables were prognostic factors for OS, whereas other variables didn't obtain statistical difference." (PMID 28881716, 2017). "Further, elevated expression of FcRn, but not of a mutated variant (H166A) that does not interact with albumin whilst retaining IgG binding, leads to substantially slower tumor growth rates." (PMID 27974681, 2017). "This leads to the possibility that this complex may be involved in receptor-mediated uptake of albumin into tumor cells." (PMID 27974681, 2017). "Ras-driven cancer cells are also known to have increased lipid scavenging to support tumor metabolism, and although the mechanisms remain to be elucidated, it is reasonable to hypothesize that serum lipids bound to albumin are taken up via macropinocytosis." (PMID 29085336, 2017). "In conjunction with systemic therapies, baseline albumin level, primary renal lesion necrosis diameter, and primary renal lesion tumor diameter and necrosis change during first-line systemic therapy predict disease prognoses in a simpler and more efficient manner." (PMID 28562690, 2017). "In addition to the reducibility, also the tumor-targeting potential of the albumin-bound drugs 24 h after i.v. administration distinctly varied." (PMID 28507680, 2017). "Hence, it is proposed that ABD-rIL-2 will bind to albumin and accumulates inside tumor and induces recruitment of cytotoxic T cells to the tumor sites." (PMID 27805072, 2017). "Results showed that tumor size (HR = 1.36, 95% CI 1.12–1.65, P = 0.002), albumin levels (HR = 0.76, 95% CI 0.65–0.91, P = 0.002), PT (HR = 2.18, 95% CI 1.54–3.10, P = 0.0001), and AFP levels (HR = 1.13, 95% CI 1.00–1.26, P = 0.049) were independently associated with mortality after RFA for HCC." (PMID 28679433, 2017). "Another group investigated the prognostic role of inflammation based biomarkers in 181 patients with UTUC by multivariate analysis and showed that tumor location, pathologic T stage, lymphovascular invasion, margin status, and albumin level were independent contributors for survival." (PMID 29348903, 2017). "In addition, the positive rates for the three tumor markers gradually and markedly increased with increasing urinary albumin excretion." (PMID 28744310, 2017). "We next investigated whether increased tumor growth rates led to lower serum albumin levels in mice." (PMID 27974681, 2017). "Lower serum albumin can reflect tumor-bearing conditions with systemic inflammation." (PMID 29137238, 2017). "BChE and albumin were decreasing with progressive disease state reflected by tumor stage." (PMID 29113384, 2017). "To obtain better anti-tumor effects, in this study, we took advantage of a new nanotechnology to design novel artesunate-loaded bovine serum albumin nanoparticles to achieve the mitochondrial accumulation of artesunate and induce mitochondrial-mediated apoptosis." (PMID 28610396, 2017).
tumor (continued). "The choice of using azacytidine priming was to increase SPARC levels within the tumor, which may enhance accumulation of albumin-bound drugs at the tumor site." (PMID 28881739, 2017). "Furthermore, there were no significanct differences between preoperative GLRI and other clinicopathological parameters, such as age, albumin, tumor size, tumor location, LN metastasis and WHO classification (all P > 0.05)." (PMID 29042631, 2017). "Depletion of PSC and thus the stromal compartment has proven successful since the addition of the chemotherapeutic agent nab-Paclitaxel, the albumin-bound form of paclitaxel which accumulates in the tumor cells and stroma, results in better survival than chemotherapy alone." (PMID 28915646, 2017). "Consistently, tumours from HIF-1α KO mice showed an increase in extravasated albumin." (PMID 29150606, 2017). "Hypomethylating agents such as azacitidine can upregulate SPARC in tumors, which may enhance the accumulation of albumin-bound drugs at tumor site." (PMID 28881739, 2017). "Nab-paclitaxel, created with albumin-bound paclitaxel particles, has high transferability to tumour tissues and does not cause hypersensitivity reactions because of a different chemical composition compared with docetaxel and paclitaxel." (PMID 29221445, 2017). "Thus, and consistent with the xenograft experiments, FcRn expression in tumor cells reduces glutamate accumulation and proliferation in vitro when albumin is provided as an amino acid source." (PMID 27974681, 2017). "Previous studies reported the serum albumin level, serum alpha fetoprotein level, recurrent tumor size, time interval from primary hepatectomy to first recurrence, and time interval from treatment of recurrent HCC to second recurrence were significant prognostic factors to overall survival." (PMID 29262662, 2017). "Thus, both the increasing of C-reactive Protein (CRP) and interleukins and albumin decreasing should be correlated to the advanced tumor stage and poor prognosis." (PMID 27036213, 2016). "Univariate analysis revealed that HBeAg, HBV DNA level, tumor size, tumor number, pathologic differentiation grade, microvascular thrombus, aspartate aminotransferase (AST) level, albumin (ALB) level, antiviral treatment, and recurrence were associated with OS." (PMID 26992891, 2016). "Because SPARC mediates albumin transport, it may facilitate entry of albumin-bound paclitaxel into the tumor cells." (PMID 27544129, 2016). "We also founded that serum total bilirubin concentration, serum albumin level and greater tumor extent were related to poor prognosis variables, indicating that the long-term survival of patients with HCC was associated not only with the tumor but with liver function." (PMID 27387757, 2016). "Meanwhile, we evaluated the effects of eHSA supplement on blood albumin level in mice with tumor." (PMID 27895586, 2016). "Additionally, low serum albumin, elevated tumour markers CA19-9 and CEA, as well as a larger lymph-node ratio (LNR, N0 / ≤ 0.2 / > 0.2), no adjuvant chemotherapy, and R1 resection margin status were associated independently with a grim postoperative outcome." (PMID 27632196, 2016). "A preliminary study showing that SPARC-positive cancer patients had a higher response to an Abraxane®, supports the hypothesis that SPARC mediated accumulation of albumin in tumours increases the effectiveness of albumin-bound paclitaxel." (PMID 26925240, 2016). "First, tumor burden as an indicator of disease burden and health status could already be represented by albumin and BALP in the model." (PMID 27329360, 2016). "SPARC has been hypothesized to enhance tumour uptake of an albumin-based nanoparticle system of nab-paclitaxel (Abraxane®) though direct evidence remains to be elucidated." (PMID 26925240, 2016). "Importantly, low GSTA1 expression in HCCs was proportional to high tumor size and low expression of the liver-enriched genes albumin and procollagen type XVIII." (PMID 27936036, 2016).
tumor (continued). "Univariate analyses revealed that an increase in the IL-6 level was associated with low levels of albumin (<4.0 g/dL), high serum CRP (≥0.5 mg/L), high serum CEA (≥5.0 ng/dL), high serum CA19-9 (≥37 ng/dL), venous invasion, tumor depth of pT4 disease, distant metastasis, and colorectal obstruction." (PMID 26858756, 2016). "As a result, binding to albumin, though desirable for the tumor selectivity it may mediate in vivo, seems disadvantageous in vitro as it leads to decreased activity of the compound." (PMID 26988975, 2016). "However, this is the first study in the literature using albumin MBs to separate and sort the CSCs from different tumor cell subtypes." (PMID 25993512, 2015). "In the univariate analyses, directions of the hazard ratios for age, sex, CPS, MELD, bilirubin, albumin, tumor number, tumor size, AFP, extrahepatic metastasis, and vascular invasion were in agreement with the results of the MESIAH, though their magnitudes were slightly different." (PMID 26488298, 2015). "The GPS based on CRP and serum albumin reflects the systemic inflammatory response to cancer, and its proven prognostic value in cancer patients augments the contributory role of inflammation to tumor aggressiveness." (PMID 25966773, 2015). "Our study suggested that the time of peak tumor uptake of Fab fragments and other biomolecules in tumor detection was proportionate to their elimination half-lives in the blood, including ~1 h for Fab fragments and 4–5 h for serum albumin and streptavidin." (PMID 25901755, 2015). "It is hypothesized that nab-paclitaxel utilizes the endogenous transport pathways of albumin to achieve enhanced drug delivery and tumor tissue distribution." (PMID 26231955, 2015). "However, the precise mechanism and full effect of albumin-facilitated paclitaxel tumor delivery with nab-paclitaxel have yet to be completely elucidated." (PMID 26231955, 2015). "Albumin is a good indicator of hepatic protein synthetic capacity, as well as a useful marker for the host inflammatory response, which is crucial in tumorigenesis from tumour initiation to metastatic dissemination." (PMID 25737613, 2015). "In the multivariable Cox regression models, among all 13 variables tested, 8 variables (tumor size, tumor capsule, pathological grades, AFP, ALB, PT, TBIL, and tumor number) were independent risk factors for OS and were incorporated into the nomogram to predict survival for an individual." (PMID 25776856, 2015). "Treatment allocation (HR = 1.999, 95 % CI = 1.341–2.980, P = 0.001), albumin level (HR = 1.723, 95 % CI = 1.167–2.543, P = 0.006), tumor size (HR = 1.877, 95 % CI = 1.255–2.806, P = 0.002), and tumor number (HR = 1.359, 95 % CI = 1.114–1.658, P = 0.002) were independent prognostic factors for RFS." (PMID 26063407, 2015). "In order to utilize FA-FR binding specificity to achieve targeted delivery of drugs into tumor cells, we prepared Gefitinib loaded folate decorated bovine serum albumin conjugated carboxymethyl-β-cyclodextrin nanoparticles for enhancing drug delivery in cancer cells." (PMID 25358257, 2014). "The baseline characteristics of patients in the HAIC group and the symptomatic treatment group were similar in age, sex, tumor size, tumor number, the presence of main portal vein invasion, albumin level, bilirubin level, Child classification, Okuda stage, CLIP score, and BCLC stage." (PMID 24824520, 2014). "To elucidate its clinical significance we evaluated the association between PN expression and clinicopathological characteristics, including age, sex, location, pathologic subtype, tumor size, Enneking stage, alkaline phosphatase, serum albumin and erythrocyte sedimentation rate (ESR)." (PMID 25224568, 2014). "The overall albumin-Gd-DTPA enhancement in the tumor core was very low." (PMID 24466160, 2014). "Moreover, studies have suggested that the hypoalbuminiemia evident in cancer patients is a result of albumin catabolism by the tumor." (PMID 25161624, 2014).